GPR143 (G protein-coupled receptor 143)
Diseases named in the same sentence as GPR143 in open-access papers (continued):
Sharing a sentence is not in itself a finding about the gene and the disease.
Nystagmus (17 papers, 2008 to 2025). Rhythmic, involuntary oscillations of one or both eyes related to abnormality in fixation, conjugate gaze, or vestibular mechanisms. "In conclusion, hemizygous variants in GPR143 have been shown in the literature to be strongly associated with infantile-onset nystagmus, reduced vision, and foveal hypoplasia with varying degrees of iris and fundus hypopigmentation." (PMID 40869959, 2025). "Mutations in the G-protein coupled receptor 143 (GPR143) gene, which is positioned at Xp22.2, are largely associated with OA, with nystagmus occurring as a secondary symptom." (PMID 36833273, 2023). "In our study, we have identified a novel mutation of GPR143 in Chinese family with nystagmus-free foveal hypoplasia, which further expanded the genetic mutation spectrum." (PMID 33785018, 2021). "It is believed that nystagmus, foveal hypoplasia, and hypopigmentation in the fundus are all associated with GPR143 mutations." (PMID 33732697, 2021). "Foveal hypoplasia from GPR143 variants is usually associated with conditions, such as eye albinism and nystagmus." (PMID 33785018, 2021). "We present a case of a diagnosis of GPR143-associated OA in an adolescent Hispanic male with infantile-onset nystagmus with prior negative genetic testing during infancy and a significant family history of nystagmus in maternal male relatives." (PMID 40869959, 2025). "These two reports did not present sufficient clinical data to evaluate their hypothesis of isolated nystagmus from GPR143 variants." (PMID 22916221, 2012). "However, the exact molecular mechanism of how the mutated GPR143 causes ocular abnormalities, such as nystagmus and macular hypoplasia, is still unknown." (PMID 26160353, 2015). "Equally, loci associated with foveal hypoplasia, nystagmus and hypopigmentation (AHR, FRMD7, GPR143, and SLC38A8) were assessed for SNV or SV segregating with disease." (PMID 38383453, 2024). "More than 100 mutations of GPR143 have been detected in family and sporadic cases, which is commonly associated with OA1 characterized by nystagmus, ocular hypopigmentation and foveal hypoplasia." (PMID 33785018, 2021). "The mutation of GPR143 leaded to OA1, an X-linked type of albinism, which results in nystagmus, impaired visual acuity and foveal hypoplasia." (PMID 33785018, 2021). "The other family had a 19 bp duplication in exon 1 of GPR143 and all affected individuals exhibited nystagmus." (PMID 22916221, 2012). "Together, our results presented this previously unidentified mutation of GPR143 that caused the isolated foveal hypoplasia without nystagmus." (PMID 33785018, 2021). "In this study, we reported a novel nonsense mutation of GPR143 in a large family with poor visual acuity and isolated foveal hypoplasia without nystagmus, which further expanded the genetic mutation spectrum of GPR143." (PMID 33785018, 2021). "Pigmentation loss in the iris and retina is usually not obvious in Asian individuals, therefore, nystagmus may be the main manifestation in patients with GPR143 mutations." (PMID 33732697, 2021). "Up to date, more than one hundred mutations in the GPR143 gene have been identified in OA1 in the world, but GPR143 variants without nystagmus have been rarely reported." (PMID 33785018, 2021).
melanoma (13 papers, 2009 to 2024). A malignant, usually aggressive tumor composed of atypical, neoplastic melanocytes. "Next, we used MNT1 melanoma cells that stably express melanosomal protein GPR143 fused to the red fluorescent protein RFP to track melanosome movement." (PMID 38719996, 2024). "Among these genes, the transcription factor MITF, the pigmentation enzyme TYR, and MLANA and GPR143 that are involved in melanosome biogenesis, are important players in melanoma." (PMID 25207815, 2014). "Of all the genes tested, DCT had the strongest negative time effect at 3 mg/kg, followed by solute carrier family 45, member 2 (a protein that is present in a high percentage of melanoma cell lines), G protein-coupled receptor 143, and carbonic anyhydrase XIV." (PMID 22123319, 2011). "In addition, the study revealed that GPR143-induced melanoma cell metastasis activated the RAS/RAF/MEK/ERK signaling pathway." (PMID 35495622, 2022). "Upregulation of GPR143 in chemoresistant melanoma may thus be due to upregulation of MITF, since MITF directly controls GPR143 expression." (PMID 35495622, 2022). "GPR143 promotes migration and chemotherapeutic resistance of melanoma cells." (PMID 31765370, 2019). "Furthermore, six SNPs in TYR, SILV/CDK2, GPR143, and F2RL1 showed strong differences in melanoma risk by sex (P < 0.01)." (PMID 26998216, 2016). "GPR143 may also play a role in melanomagenesis and melanoma progression." (PMID 35495622, 2022). "Further, we detected signature melanosomal markers TYR, DCT, GPR143, and GPNMB in the melanosomes derived from melanoma cells, fibroblasts and keratinocytes (Fig. EV2I)." (PMID 38719996, 2024). "For instance, in skin cutaneous melanoma (SKCM), ADGRG1/GPR56, GPR143, and EDNRB are highly overexpressed and highly expressed in magnitude compared to normal skin in >90% of melanoma samples." (PMID 31765370, 2019). "The remaining five receptors (DRD2, FZD4, GPR143, GPR161, and SMO) may be of interest in the context of melanoma, but they have not been studied yet." (PMID 35158973, 2022).
congenital nystagmus (11 papers, 2008 to 2023). Nystagmus present at birth or caused by lesions sustained in utero or at the time of birth. "Our results provide additional evidence that mutations in GPR143 are another cause of congenital nystagmus in the Chinese population." (PMID 19390656, 2009). "We believe that further biochemical studies of the mutations in GPR143 will yield insight into its molecular mechanism underlying the pathogenesis of congenital nystagmus." (PMID 19390656, 2009). "However, it is easily misdiagnosed as congenital idiopathic nystagmus in some Chinese patients with OA1 caused by the G-protein coupled receptor 143 (GPR143) gene mutations." (PMID 26160353, 2015). "Our results indicate that this novel GPR143 mutation might be associated with the congenital nystagmus observed in this Chinese family." (PMID 19390656, 2009). "Moreover, another GPR143 14 bp deletion mutation in exon 6 was also identified in white males in a family with X-linked congenital nystagmus." (PMID 19390656, 2009). "However, there were only nine different GPR143 mutations identified in the Chinese population, two of which were described in two families with X-linked congenital nystagmus." (PMID 19390656, 2009). "In addition, the Chinese population might have a variant phenotype of mutation in GPR143 with congenital nystagmus as the most prominent and only consistent finding." (PMID 18523664, 2008). "X-linked IIN (XLIIN) is the most common form of congenital nystagmus, and the FERM domain-containing gene (FRMD7) is the most common cause of pathogenesis, followed by mutations in GPR143." (PMID 37545716, 2023). "Idiopathic congenital nystagmus (ICN) is an ocular movement disorder and X-linked inheritance mode is more common, accounting for about 90% of cases, and the main pathogenic genes are FRMD7 and GPR143, with variants in the FRMD7 gene being more common." (PMID 37749571, 2023). "In addition, the patients carrying GPR143 mutations had macular hypoplasia obtained by OCT, which further supported clinically that congenital nystagmus in these patients sensory defect type and caused by the maldevelopment of the macular or visual pathways." (PMID 26160353, 2015). "For the molecular diagnosis of this pedigree, the FRMD7 gene (candidate gene for congenital nystagmus) and GPR143 gene (candidate gene for OA1) were analyzed." (PMID 22916221, 2012).
Parkinson disease (3 papers, 2019 to 2025). A progressive degenerative disorder of the central nervous system characterized by loss of dopamine producing neurons in the substantia nigra and the presence of Lewy bodies in the substantia nigra and locus coeruleus. "GPR143 is widely expressed in neurons in several regions of the brain and may play a role in the etiology of Parkinson’s disease (PD)." (PMID 35495622, 2022). "The GPR143 ligand, L-DOPA, is produced during melanin synthesis and Parkinson’s disease patients taking L-DOPA showed reduced/delayed onset of AMD, suggesting that signalling from GPR143 might protect from AMD." (PMID 40970089, 2025).
age-related macular degeneration (2 papers, 2021 to 2023). Age-related loss of vision in the central portion of the retina (macula), secondary to retinal degeneration. "As for the effect on macular pigment, increasing evidence have been shown that GPR143 activity may protect against both onset and progression of age-related macular degeneration (AMD)." (PMID 33785018, 2021). "The activation of GPR143 also triggers a reduction in the vascular endothelial growth factor (VEGF); it has therefore been proposed as a potential treatment for age-related macular degeneration (AMD)." (PMID 37759997, 2023).
ptosis (2 papers, 2019 to 2022). The drooping of the upper eyelid. "Since L-DOPA induced ptosis in both WT and GPR143-KO mice, the authors suggest that there may be GPR143-dependent and independent mechanisms for inducing ptosis." (PMID 35495622, 2022). "Although GPR143 is the most plausible l-DOPA receptor candidate, we found that l-DOPA induced ptosis in GPR143-KO as well as Wt mice pretreated with a central AADC inhibitor." (PMID 31632270, 2019).
Strabismus (2 papers, 2020 to 2021). A misalignment of the eyes so that the visual axes deviate from bifoveal fixation. "We identified a novel 3,923 kb deletion within the Xp22.31 region (chrX: 5810838–9733877) containing STS, ANOS1, GPR143, NLGN4X, VCX-A, PUDP, and PNPLA4 in patient 1, who presented with KS, XLI, obesity, hyperlipidemia, and strabismus." (PMID 32670353, 2020).
Anxiety (1 paper, 2026). Intense feelings of nervousness, tension, or panic often arise in response to interpersonal stresses. "Overall, these results suggest that Gpr143−/y mice exhibit a mix of sensorimotor gating and minor cognitive abnormalities, consistent with schizophrenia, and increased reward‐seeking, aggressive, and anxiety‐related behaviors (consistent with a mood or affective disorder)." (PMID 41510670, 2026).
breast carcinoma (1 paper, 2024). "In addition, exposure of MCF7 cells to EVs derived from GPR143-overexpressing breast cancer cells (MCF-7) enhanced their migration and invasion compared to EVs from shRNA against GPR143 containing cells, while exposure of HUVEC cells to the former EVs promoted their vascular branching." (PMID 39698539, 2024).
depression (1 paper, 2026). "In the forced swim test, Gpr143−/y mice became immobile more rapidly and for longer than Wt mice, indicating a greater degree of behavioral despair and depression than Wt mice, suggestive of a mood or affective disorder." (PMID 41510670, 2026). "In this test, Gpr143−/y mice exhibited increased immobility time compared to Wt mice, a sign of depression." (PMID 41510670, 2026). "In adult Gpr143−/y mice, hippocampal neurogenesis was decreased during development and adulthood, and these mice showed exacerbated depression‐like behavior." (PMID 41510670, 2026).
Exotropia (1 paper, 2021). A form of strabismus with one or both eyes deviated outward. "In the GPR143 group, two patients (100%) (test data were not available in the other three patients) with OA and exotropia were found to have no stereopsis in either TNO or Titmus test." (PMID 33732697, 2021).
Idiopathic infantile nystagmus (1 paper, 2020). "Idiopathic infantile nystagmus (IIN) is a high genetically heterogeneous ophthalmic disease and is often associated with pathogenic mutations in FRMD7 and GPR143, respectively." (PMID 31495972, 2020).
lung carcinoma (1 paper, 2019). "Besides, CCR7, CST7, GPR143, HDAC5, and IDO1 are also related to lung cancer or the MAPK pathway." (PMID 30972101, 2019).
macular degeneration (1 paper, 2022). Loss of vision in the central portion of the retina (macula), secondary to retinal degeneration. "Numerous additional roles have been proposed for GPR143 in determining cancer predisposition, regulation of blood pressure, development of macular degeneration and signaling in the brain, which we will briefly describe as well as potential ligands that have been identified." (PMID 35495622, 2022).
melanosis (1 paper, 2023). "TYRP1, MC1R, and GPR143 genes are thought to play an important role in the process of melanosis in chickens." (PMID 37235424, 2023).
nicotine addiction (1 paper, 2021). "In addition to its role in pigment cells, GPR143 has also been shown to mediate depressor response in the brain stem solitary nucleus, is expressed in several regions of the central nervous system such as the hippocampus, and, most recently, GPR143 was shown to be associated with nicotine addiction." (PMID 34361094, 2021).
PEComas (1 paper, 2025). "PEComas are also characterized by specific transcriptomic features of the overexpressed DAPL1, MLANA, SULT1C2, GPR143 and CHI3L1 genes, as well as epigenetic features of lysosomal and melanocyte proteins as biomarkers." (PMID 40989692, 2025).
schizophrenia (1 paper, 2026). A major psychotic disorder characterized by abnormalities in the perception or expression of reality. "The startle response amplitudes were higher in Gpr143−/y mice than in Wt mice, and the percentage of PPI was reduced, indicating impaired sensorimotor gating, a phenotype associated with schizophrenia." (PMID 41510670, 2026). "For example, neuronal HB‐EGF has been found to be upregulated in schizophrenia, and similarly seen in our Gpr143−/y mice, and in these studies of schizophrenic patients, serum EGF levels were negatively correlated with cognition in patients with schizophrenia." (PMID 41510670, 2026).
Stickler syndrome (1 paper, 2024). Stickler syndrome is an inherited vitreoretinopathy characterized by the association of ocular signs with more or less complete forms of Pierre-Robin sequence, bone disorders, and sensorineural deafness (10% of cases). "Exome sequencing identified 21 potential pathogenic variants of 13 genes in 20 of 75 (26.7%) probands, including genes for Stickler syndrome (COL11A1 and COL2A1; 6/20), FEVR (FZD4, LRP5, and TSPAN12; 5/20), and others (FBN1, GPR179, ZEB2, PAX6, GPR143, OPN1LW, FRMD7, and CACNA1F; 9/20)." (PMID 38243264, 2024).
cancer (3 papers, 2019 to 2025). A tumor composed of atypical neoplastic, often pleomorphic cells that invade other tissues. "GPR143 is elevated in multiple cancers, where GPR143-ESCRT pathway promotes the secretion of EVs that carry unique cargo, including integrins and signaling proteins." (PMID 40108630, 2025). "In a recent bioinformatic analysis investigating unilateral and bilateral retinoblastoma microarrays, GPR143 was identified as a potential biomarker for the cancer." (PMID 35495622, 2022). "Genome-wide association studies also identified GPR143 and its neighbor SHROOM2 as susceptibility genes for cancer." (PMID 35495622, 2022). "GPR143 and hsa-mir-378 pair was also in common between LIHC_57, KIRC_33, and KIRP_49, which indicate these cancer clusters could have common driving transcription regulation patterns due to the fact that they share common miRNA–mRNA pairs." (PMID 31514484, 2019).
tumor (2 papers, 2019 to 2021). "In SKCM, which has the highest mutation burden among TCGA tumor types, the most highly overexpressed GPCRs (GPR143, EDNRB, and GPR56) are mutated in <2% of SKCM tumors, whereas frequently mutated GPCRs (e.g., GPR98, mutated in nearly 40% of tumors) typically have low expression." (PMID 31765370, 2019). "One study demonstrated that GPR143 was the most highly upregulated GPCR in SKCM and suggested that GPCR mRNA signatures characterize specific tumor types." (PMID 34722301, 2021).
GPR143 also shares sentences with these, for which no sentence is quoted: oculocutaneous albinism (3 papers); Griscelli syndrome (2); achromatopsia (1); Aland island eye disease (1); autism (1); blue cone monochromacy (1); cataract (1); colorectal cancer (1); congenital cataract (1); degenerative diseases (1); familial adenomatous polyposis syndrome (1); hepatoma (1); hyperlipidemia (1); Intellectual disability (1); lysosome-related organelle disorders (1); Obesity (1); Onset (1); prostate carcinoma (1); Psychosis (1); Retinal dystrophy (1); retinopathy (1); skin cutaneous melanoma (1); Stroke (1); visual disorder (1); vitiligo (1); X-linked recessive chondrodysplasia punctata (1); X-linked retinoschisis (1).